LRG1 (leucine rich alpha-2-glycoprotein 1)
Diseases named in the same sentence as LRG1 in open-access papers (continued):
Sharing a sentence is not in itself a finding about the gene and the disease.
ovarian carcinoma (continued). "Ovarian cancer cells secrete LRG1 and may contribute directly to the elevated levels of LRG1 observed in the serum of ovarian cancer patients." (PMID 20831812, 2010). "Though future studies using a larger patient cohort are needed to determine whether LRG1 may serve as a biomarker for presurgical diagnosis of ovarian cancer, for the detection of recurrent disease, and/or as a target for therapeutic treatment, these initial results are encouraging." (PMID 20831812, 2010). "Furthermore, we showed the expression of LRG1 mRNA and protein in ovarian cancer tissues and cell lines, signifying that the tumor cells could be contributing to the increased levels of LRG1 in sera of ovarian cancer patients." (PMID 20831812, 2010). "Likewise, LRG1 may be a survival factor for ovarian cancer cells, possibly rendering them more resistant to chemotherapy." (PMID 20831812, 2010). "This hypothesis is supported by our Western blot findings that an ~51 kD band was found in the conditioned media of the NIH:OVCAR5 cells but not the NOSE cells, again suggesting that the ~51 kD glycoform of LRG1 may be preferentially secreted, or aberrantly glycosylated in ovarian cancer." (PMID 20831812, 2010). "Mass spectrometry analysis of urinary exosomes from 10 epithelial ovarian cancer (EOC) patients and 10 healthy controls revealed increased expression of leucine-rich alpha-2-glycoprotein 1 (LRG1) in EOC patients." (PMID 40075875, 2025). "Overexpression of LRG1 has been found in multiple cancers such as pancreatic ductal adenocarcinoma (PDAC) and ovarian cancer, where it promotes cell proliferation, migration and invasion." (PMID 34930899, 2021). "LRG1 expressed more highly in non-small cell lung cancer (NSCLC), small cell lung cancer (SCLC), hepatocellular carcinoma (HCC), ovarian cancer, endometrial carcinoma tissues and serum than matched normal spices." (PMID 29029535, 2017). "Although LRG1 has been classified as an "acute phase" protein, produced by the liver in response to injury or infection, we have evidence that LRG1 is also being produced by ovarian cancer cells and may contribute to the increased levels of LRG1 found in patient sera (manuscript in preparation)." (PMID 20546617, 2010). "Indeed, we showed that glycosidase treatment of LRG1, both purified and in extracts of ovarian cancer and NOSE cell lines, reduced the apparent molecular weight of LRG1 indicating the presence of carbohydrate modifications of the protein backbone." (PMID 20831812, 2010). "LRG1 mRNA expression was observed in 7 of the 12 ovarian cancer cell lines tested, but no measurable expression was detected in the 4 immortalized NOSE cell lines." (PMID 20831812, 2010). "Others have identified LRG1 peptides by mass-spectrometry in the secreted or cell surface fractions of CAOV3 and OVCAR3 serous ovarian cancer cell lines, but not in the clear cell ovarian cancer cell line ES-2." (PMID 20831812, 2010).
diabetic nephropathy (19 papers, 2018 to 2025). "The elevated levels of LRG1 in diabetic nephropathy are associated with glomerular neovascularization and podocyte loss." (PMID 39845838, 2024). "It is interesting to note that in streptozotocin (STZ)-induced diabetic mouse models, LRG1 loss of function had a protective role in development of diabetic nephropathy." (PMID 36346018, 2022). "Our findings suggest, therefore, that LRG1 might be associated with increased excretion of urinary albumin in the early stages of diabetic nephropathy." (PMID 37916147, 2023). "This study suggests that LRG1 may be associated with increased excretion of urinary albumin in the early stages of diabetic nephropathy." (PMID 37916147, 2023). "In addition, several studies have reported that LRG1 may be implicated in diabetic nephropathy progression." (PMID 37916147, 2023). "The ablation of LRG‐1 in diabetic kidney disease reduces not only glomerular angiogenesis but also attenuates foot process effacement, podocyte loss, and mesangial expansion, suggesting a role of LRG‐1 in the cross‐talk between GEnCs and podocytes." (PMID 40698593, 2025). "LRG1 is synergistically affected in the progression of diabetic kidney disease (DKD) via TGF‐β/activin receptor‐like kinase 1 (ALK1) signaling." (PMID 38656694, 2024). "The leucine-rich α-2-glycoprotein 1 (LRG1) is a proangiogenic factor that potentiates diabetic kidney disease." (PMID 38610646, 2024). "The role of LRG1 in kidney disease, in particular diabetic nephropathy, is gaining interest with growing evidence that LRG1 contributes to vascular rarefaction and abnormal neovascularization." (PMID 38745756, 2024). "In the kidney, LRG1 is primarily localized in renal glomeruli and its level rises in diabetic nephropathy." (PMID 39845838, 2024). "LRG1 is remarkably expressed in the glomerular endothelial cells and tubulointerstitial segment of nephrons in diabetic nephropathy." (PMID 36818747, 2023). "Thus, the association between LRG1 level and urinary albumin excretion observed in our study might be partially accounted for by these factors, because these contribute to an increased risk of diabetic nephropathy as well." (PMID 37916147, 2023). "One of the most compelling roles for LRG1 is its involvement in promoting diseased vessels in a wide variety of pathological settings, including diabetic nephropathy, diabetic retinopathy, age-related macular degeneration, and cancer." (PMID 35062948, 2022). "LRG1 was a novel proangiogenic factor involved in abnormal angiogenesis and renal fibrosis in diabetic nephropathy." (PMID 35095520, 2021). "Our previous study showed that LRG1 promoted diabetic kidney disease (DKD) progression by enhancing TGF-β-induced angiogenesis." (PMID 32337221, 2020). "We also found that LRG1 promoted diabetic kidney disease progression by enhancing TGF-β–induced angiogenesis." (PMID 32337221, 2020). "Nevertheless, the findings of the present study provide important information regarding the pathogenesis of abnormal angiogenesis in early stage diabetic nephropathy, suggesting that LRG1 is a novel preemptive therapeutic target in diabetic nephropathy." (PMID 30515388, 2018). "At 24 weeks, the features of early diabetic nephropathy in db/db mice had developed further, along with further enhanced glomerular LRG1 expression." (PMID 30515388, 2018). "The aim of this study was to compare glomerular expression of the classical proangiogenic factor VEGF and novel proangiogenic factor LRG1 in the early stage of diabetic nephropathy." (PMID 30515388, 2018). "In the present study, we investigated the intrarenal expression and distribution of a novel proangiogenic factor, LRG1, along with the development of early stage diabetic nephropathy." (PMID 30515388, 2018). "Very recently, Leucine-rich α-2-glycoprotein-1 (LRG1), a novel proangiogenic factor expressed in endothelial cells, has been reported to be involved in the development of diabetic nephropathy." (PMID 30515388, 2018).
diabetic nephropathy (continued). "The features of early diabetic nephropathy in db/db mice had developed further, along with further enhanced glomerular LRG1 expression at 24 weeks of age." (PMID 30515388, 2018). "Transcriptomic and in vitro analyses revealed that LRG1 in glomerular endothelial cells is one of the key regulators in the development of abnormal angiogenesis at the early stage of diabetic nephropathy." (PMID 30515388, 2018). "In the present study, we investigated intrarenal expression of the novel proangiogenic factor LRG1 in diabetic db/db mice by immunohistochemistry and a laser capture microdissection method during the development of diabetic nephropathy." (PMID 30515388, 2018). "LRG1 was formerly assumed to be involved in ocular neovascularization, but more recent research has revealed links to psoriasis, rectal cancer, atherosclerosis, and diabetic nephropathy 135-138." (PMID 40860185, 2025). "Indeed, a transcriptomics study has shown that in a model of diabetic nephropathy, Lrg1 was upregulated in glomerular endothelial cells, where it mediated high glucose-induced pathological angiogenesis." (PMID 38745756, 2024). "An intriguing aspect of LRG1 in diabetic nephropathy is that LRG1 expression rises before VEGF levels, and targeting LRG1 may be a logical step in preventing diabetic nephropathy before significant kidney damage occurs." (PMID 39845838, 2024). "Interestingly, it has been elucidated that increased expression of leucine-rich α-2 glycoprotein-1 (LRG1) worsens the outcome of diabetic nephropathy." (PMID 36818747, 2023). "However, further large-scale longitudinal studies are necessary to elucidate the precise role of LRG1 in early-stage diabetic nephropathy." (PMID 37916147, 2023). "Our results suggest that LRG1 level may be an early indicator of diabetic nephropathy in patients with T2DM." (PMID 37916147, 2023). "This is currently most evident in the eye and kidney, where it plays a central role in the vascular dysfunction observed in models of retinal neovascularisation and diabetic kidney disease and is consistent with raised LRG1 levels in patients with these diseases." (PMID 35318338, 2022). "Interestingly, in other fibrotic conditions, including idiopathic pulmonary fibrosis and diabetic nephropathy, LRG1 has been reported to drive fibrosis by modulating TGF-β signaling." (PMID 34445590, 2021). "Thus, there is the possibility that the abnormal angiogenesis observed in the very early stage of diabetic nephropathy in db/db mice was attributed to LRG1." (PMID 30515388, 2018). "We hypothesized that glomerular LRG1 expression is increased earlier than VEGF expression under conditions of pathological angiogenesis in the early stage of diabetic nephropathy." (PMID 30515388, 2018). "Therefore, the functional role of LRG1 in abnormal angiogenesis in the early stage of diabetic nephropathy must be investigated further using LRG1 transgenic and knockout mice." (PMID 30515388, 2018). "We investigated glomerular expression of VEGF and LRG1 in a mouse model of diabetes (C57BL/KsJ-db/dbJcl; db/db mouse) and compared the changes in expression at 16 and 24 weeks of age to evaluate their association with diabetic nephropathy development." (PMID 30515388, 2018). "Similarly, other studies have also shown that in experimental diabetic kidney disease (DKD) Lrg1 gene expression induced in glomerular endothelial cells is involved in vascular rarefication and subsequent neovascularization and fibrosis, partly via activation of the p38 and TGF-β-SMAD1/5/8 pathway." (PMID 38745756, 2024). "Potential mechanisms could link LRG1 to diabetic nephropathy." (PMID 37916147, 2023). "This is based on the finding that LRG1 expression precedes the expression of VEGF and its receptor VEGFR-2 in diabetic nephropathy and that VEGF is expressed mainly in the injured podocytes following endothelial injury." (PMID 38745756, 2024).
diabetic nephropathy (continued). "However, it has not been clarified whether LRG1 is implicated in early-stage diabetic nephropathy in T2DM patients." (PMID 37916147, 2023). "Our previous work demonstrated that LRG1 significantly accelerated diabetic kidney injury and TGF-β/ALK1-induced angiogenesis in an experimental model of early diabetic kidney disease." (PMID 32337221, 2020). "In this study, we demonstrated for the first time that glomerular LRG1 expression was increased earlier than VEGF and VEGFR-2 expression under the conditions of pathological angiogenesis in the early stage of diabetic nephropathy." (PMID 30515388, 2018). "However, the pathophysiology of LRG1 in diabetic nephropathy remains largely unknown." (PMID 30515388, 2018). "However, the pathophysiology of LRG1 in diabetic nephropathy is still largely unknown." (PMID 30515388, 2018). "LRG‐1 is mainly expressed in GEnCs and not in podocytes and promotes the progression of diabetic kidney disease by enhancing angiogenesis through TGF‐β/ALK1." (PMID 40698593, 2025). "Our most important finding is that the increase in LRG1 expression of glomerular endothelial cells precedes the increase in VEGF expression, which is another proangiogenic factor involved in the development of diabetic nephropathy." (PMID 30515388, 2018).
hepatocellular carcinoma (18 papers, 2010 to 2025). A malignant tumor that arises from hepatocytes. "As a matter of fact, a wide range of diseases, including retinoblastoma, respiratory inflammatory disorder, hepatocellular carcinoma, ulcerative colitis and heart failure, have been linked to elevated serum LRG1 levels in numerous clinical reports." (PMID 37048540, 2023). "For example, in human hepatoma cells, induction of LRG1 expression has been associated with loss of TGFβ-mediated growth inhibition." (PMID 35062948, 2022). "The impact of LRG1 on cell migration and invasion appeared to be controversial even in the same tumor type, such as hepatocellular carcinoma (HCC)." (PMID 32047555, 2020). "This appeared to be consistent with previous publications demonstrating a potential tumor-promoting effect of LRG-1 on other malignancies, such as hepatocellular carcinoma, glioblastoma and colon cancer." (PMID 30760292, 2019). "LRG1 is also increased in serum of patients with hepatocellular carcinoma following therapeutic ablation treatment." (PMID 20831812, 2010). "Indeed, several in vitro studies described IL-1β, IL-17, TNFα, IL-4, IL-33 and IL-10 as additional LRG1 regulators in hepatoma cells, endothelial cells, bronchial epithelial cells and “alternatively activated” (M2) macrophages." (PMID 35062948, 2022). "There is recent evidence that LRG1 is induced by IL-6 and synergistically up-regulated with either IL-1β or tumor necrosis factor-α in a pattern similar to that exhibited by type 1 acute-phase proteins in human hepatoma HepG2 cells." (PMID 29513714, 2018). "Migration and invasion of hepatocellular carcinoma cells are suppressed by LRG1." (PMID 29190982, 2017). "However, LRG1 has been reported to act as a tumor suppressor in hepatocellular carcinoma and endometrial carcinoma." (PMID 26856989, 2016). "There are also contradictory findings showing that LRG1 suppresses migration and invasion of esophageal squamous cell carcinoma (ESCC) and hepatocellular carcinoma (HCC)." (PMID 34930899, 2021). "LRG1 mRNA level is upregulated in most hepatocellular carcinoma (HCC) cell lines." (PMID 29206167, 2017).
Sepsis (18 papers, 2019 to 2026). Sepsis is defined as life-threatening organ dysfunction caused by a dysregulated host response to infection. "This pilot study indicated that serum LYZ and LRG1 levels were significantly associated with sepsis recovery contributed by CRRT in pediatric patients." (PMID 36650427, 2023). "Among 5,607 DEGs, Lrg1, Ace2, Itgb6, Hmgb2, Pik3r5, Itgam, Plcb1, Jak2, Vegfa, and Hif1α were associated with the entire course of sepsis-induced myocardial injury, which have been reported previously." (PMID 35721566, 2022). "Elevated serum LYZ and LRG1 levels are associated with clinical benefits of CRRT during sepsis." (PMID 36650427, 2023). "Finally, ANKRD22, GPR84, GYG1, BLOC1S1, CARD11, NOG, and LRG1 were recognized as critical genes associated with sepsis molecular subtypes." (PMID 36035194, 2022). "Secondly, among screened 6 proteins, only LYZ and LRG1 were validated to be potential biomarker for assessing the progression of sepsis and clinical benefits of CRRT in pediatric patients with sepsis." (PMID 36650427, 2023). "Based on the serum proteomic analysis in patients with sepsis before and after CRRT, elevated serum LYZ and LRG1 levels are associated with clinical benefits of CRRT during sepsis recovery." (PMID 36650427, 2023). "Though confirmed in a larger-scale population, LYZ and LRG1 was screened as novel biomarkers of sepsis recovery contributed by CRRT as an adjuvant therapy." (PMID 36650427, 2023). "More importantly, Lrg1 has higher serum levels in sepsis patients and has been regarded as a potential new biomarker for sepsis." (PMID 35264055, 2022). "In GSE154918 and GSE69063 datasets, ANKRD22, GPR84, GYG1, BLOC1S1, and LRG1 were all highly expressed in sepsis patients, whereas NOG and CARD11 were dramatically decreased in sepsis patients." (PMID 36035194, 2022). "For example, Lrg1 (leucine rich alpha-2-glycoprotein 1) plays a key role in TGF-β signaling and cardiac remodeling, and increased serum Lrg1 level is associated with sepsis." (PMID 35721566, 2022). "More importantly, Lrg1 has been identified as a novel potential biomarker for sepsis through bioinformatics analysis." (PMID 35264055, 2022). "This study firstly uncovered that Lrg1 expression was definitely high in brain tissues of sepsis mice." (PMID 35264055, 2022). "The ROC (receiver operating characteristic curve) identified nine transcriptomic genes, including LRG1, as potential new biomarkers for sepsis." (PMID 35095520, 2021). "Conclusions: sCD300a, sCD300b and sCD25 could be specific serum biomarkers for HLH diagnosis, and SAA-1 and LRG1 might be useful biomarkers for differential diagnosis between sepsis and HLH." (PMID 41463121, 2025). "LYZ and LRG1 might be valuable indicators for assessing the clinical benefits of CRRT in pediatric patients with severe sepsis." (PMID 36650427, 2023). "So, we can suspect that serum LRG1 level could be another biomarker which is responsible for the clinical benefits of CRRT in pediatric sepsis." (PMID 36650427, 2023). "Thus, LRG1 can be viewed as a double-edged sword, similar to growth factors in cancers and cytokines in sepsis." (PMID 35562586, 2022). "Meanwhile, patients who suffer from sepsis have increased serum levels of Lrg1." (PMID 35264055, 2022). "We aimed to explore the effects and potential mechanism of Lrg1 on sepsis-mediated brain injury." (PMID 35264055, 2022). "According to our measurement results, uLRG1/u-Cr of sepsis patients was obviously higher in sepsis patients than in either SIRS patients or healthy volunteers (P < 0.001), indicating that urinary LRG1 is a promising biomarker in diagnosing sepsis and distinguishing sepsis from SIRS." (PMID 34675320, 2021).